OGT (O-linked N-acetylglucosamine (GlcNAc) transferase)
Description:
Catalyzes the transfer of a single N-acetylglucosamine from UDP-GlcNAc to a serine or threonine residue in cytoplasmic and nuclear proteins resulting in their modification with a beta-linked N-acetylglucosamine (O-GlcNAc). Glycosylates a large and diverse number of proteins including histone H2B, AKT1, AMPK, ATG4B, CAPRIN1, EZH2, FNIP1, GSDMD, KRT7, LMNA, LMNB1, LMNB2, RPTOR, HOXA1, PFKL, KMT2E/MLL5, MAPT/TAU, TET2, RBL2, RET, NOD2 and HCFC1. Can regulate their cellular processes via cross-talk between glycosylation and phosphorylation or by affecting proteolytic processing. Involved in insulin resistance in muscle and adipocyte cells via glycosylating insulin signaling components and inhibiting the 'Thr-308' phosphorylation of AKT1, enhancing IRS1 phosphorylation and attenuating insulin signaling (By similarity). Involved in glycolysis regulation by mediating glycosylation of 6-phosphofructokinase PFKL, inhibiting its activity. Plays a key role in chromatin structure by mediating O-GlcNAcylation of 'Ser-112' of histone H2B: recruited to CpG-rich transcription start sites of active genes via its interaction with TET proteins (TET1, TET2 or TET3). As part of the NSL complex indirectly involved in acetylation of nucleosomal histone H4 on several lysine residues. O-GlcNAcylation of 'Ser-75' of EZH2 increases its stability, and facilitating the formation of H3K27me3 by the PRC2/EED-EZH2 complex. Stabilizes KMT2E/MLL5 by mediating its glycosylation, thereby preventing KMT2E/MLL5 ubiquitination. Regulates circadian oscillation of the clock genes and glucose homeostasis in the liver (By similarity). Stabilizes clock proteins BMAL1 and CLOCK through O-glycosylation, which prevents their ubiquitination and subsequent degradation (By similarity). Promotes the CLOCK-BMAL1-mediated transcription of genes in the negative loop of the circadian clock such as PER1/2 and CRY1/2. O-glycosylates HCFC1 and regulates its proteolytic processing and transcriptional activity. Component of a THAP1/THAP3-HCFC1-OGT complex that is required for the regulation of the transcriptional activity of RRM1. Regulates mitochondrial motility in neurons by mediating glycosylation of TRAK1 (By similarity). Promotes autophagy by mediating O-glycosylation of ATG4B. Acts as a regulator of mTORC1 signaling by mediating O-glycosylation of RPTOR and FNIP1: O-GlcNAcylation of RPTOR in response to glucose sufficiency promotes activation of the mTORC1 complex. [Isoform 2]: The mitochondrial isoform (mOGT) is cytotoxic and triggers apoptosis in several cell types including INS1, an insulinoma cell line. [Isoform 4]: Has N-acetylglucosaminyltransferase activity: glycosylates proteins, such as HNRNPU, NEUROD1, NUP62 and PDCD6IP. Displays specific substrate selectivity compared to other isoforms.
Synonyms: O-GLCNAC; HRNT1; MGC22921; FLJ23071; OGT1; HINCUT-1; MRX106; XLID106
Tractability: Small molecule: a structure with a bound ligand is known; a high-quality ligand is known; it has a high-quality binding pocket. Antibody: its Gene Ontology location is reachable by antibodies, with high confidence; UniProt places it where antibodies can reach, with medium confidence; the Human Protein Atlas places it where antibodies can reach. PROTAC: UniProt records ubiquitination sites on it; ubiquitination databases record sites on it; its protein half-life has been measured; a small molecule that binds it is known.
Target class: Enzyme
Chemical probes: OSMI-4 (high quality)
Gene: Protein-coding gene on chromosome X (71,533,083 to 71,575,892, forward strand). Ensembl gene ENSG00000147162.
Subcellular location: Nucleus; Cytoplasm; Mitochondrion (Isoform 2); Membrane; Cytoplasm (Isoform 3); Cell membrane; Mitochondrion membrane; Cell projection; Cytoplasm (Isoform 4)
Subcellular location (Human Protein Atlas): Nucleoplasm; Plasma membrane
Pathways (Reactome):
Programmed Cell Death: RIPK1-mediated regulated necrosis; Regulation of necroptotic cell death
Chromatin organization: HATs acetylate histones
Gene expression (Transcription): Formation of WDR5-containing histone-modifying complexes
Metabolism of proteins: UCH proteinases
Gene Ontology:
Molecular function: phosphatidylinositol-3,4,5-trisphosphate binding; protein binding; protein O-acetylglucosaminyltransferase activity; acetylglucosaminyltransferase activity; chromatin DNA binding; glycosyltransferase activity
Biological process: apoptotic process; cellular response to glucose stimulus; negative regulation of non-canonical inflammasome complex assembly; negative regulation of proteasomal ubiquitin-dependent protein catabolic process; negative regulation of protein ubiquitination; positive regulation of proteolysis; positive regulation of TORC1 signaling; positive regulation of transcription by RNA polymerase II; positive regulation of translation; protein O-linked glycosylation; protein processing; regulation of glycolytic process; regulation of insulin receptor signaling pathway; regulation of Rac protein signal transduction; regulation of transcription by RNA polymerase II; response to insulin; circadian regulation of gene expression; hemopoiesis; mitophagy; negative regulation of cell migration; negative regulation of stem cell population maintenance; negative regulation of transcription by RNA polymerase II; negative regulation of transforming growth factor beta receptor signaling pathway; positive regulation of cold-induced thermogenesis; positive regulation of DNA-templated transcription; and 8 more
Cellular component: cytoplasm; cytosol; histone acetyltransferase complex; membrane; mitochondrion; NSL complex; nucleoplasm; nucleus; plasma membrane; protein N-acetylglucosaminyltransferase complex; protein-containing complex; mitochondrial membrane; Sin3-type complex; glutamatergic synapse; synapse
Gene-disease validity (ClinGen):
ClinGen rates the evidence that OGT causes each of these diseases.
intellectual disability, X-linked 106 (X-linked): Moderate.
Homologues: Orthologues: guinea pig OGT (99% identical), macaque OGT (99% identical), pig OGT (99% identical), dog OGT (99% identical), mouse Ogt (99% identical), rat Ogt (99% identical), rabbit OGT (99% identical), chimpanzee OGT (98% identical), tropical clawed frog ogt (95% identical), zebrafish ogt.1 (93% identical), zebrafish ogt.2 (89% identical), Drosophila melanogaster sxc (75% identical), and 1 more. Paralogues in human: TTC6 (12% identical), TTC34 (12% identical), CFAP70 (11% identical), TTC13 (10% identical), TTC7B (10% identical), TTC7A (9% identical), TMTC2 (8% identical), TTC16 (7% identical), BBS4 (7% identical), IFT88 (7% identical), TMTC4 (7% identical), TMTC1 (6% identical), and 2 more.
Diseases named in the same sentence as OGT in open-access papers:
OGT is named in the same sentence as 203 diseases in open-access papers, as found by Europe PMC text mining. Sharing a sentence is not in itself a finding about the gene and the disease. The quoted sentences say what the papers report.
breast carcinoma (69 papers, 2011 to 2026). "Abnormally expressed OGT is strongly associated with tumorigenesis, including hematological malignancies, colorectal cancer, liver cancer, breast cancer, and prostate cancer." (PMID 38931332, 2024). "KLF8 was found to be among the most upregulated genes caused by OGT overexpression in breast cancer cells, suggesting a potential regulation of KLF8 by OGT." (PMID 37152043, 2023). "Mutation of this site or pharmacological inhibition of OGT impairs MORC2-mediated breast cancer cell migration and invasion in vitro and lung colonization in vivo." (PMID 34974534, 2022). "It has been shown that decreased O-GlcNAcylation as a result of reduced expression of OGT by siRNA causes profound changes in the proteome of MCF-7 breast cancer cells." (PMID 34204801, 2021). "In breast cancer cells, increased mTOR activity is associated with elevation of total O-GlcNAcylation and increased OGT protein levels, while blocking mTOR activity with rapamycin leads to reduced O-GlcNAcylation and OGT levels." (PMID 31272438, 2019). "A recent report shows that reducing OGT expression in breast cancer cells was associated with defects in double-stand break repair, reduced cell proliferation, and increased cell senescence in vivo." (PMID 31272438, 2019). "FoxM1 plays a critical role in cancer metabolism, as the reduction of O-GlcNAc levels and OGT in cancer cells is associated with a decrease in protein expression of FoxM1 in breast cancer." (PMID 27703839, 2016). "It has been reported recently that increased levels of global GlcNAcylation and OGT are closely linked to the metastasis of breast cancer." (PMID 27009840, 2016). "Thus, our data suggests that KFL8 plays a key role in regulating CSCs phenotypes in vitro, forms a feed-forward regulation with OGT, regulates triple negative breast tumor growth in vivo and associates with poor clinical outcome in breast cancer patients." (PMID 37152043, 2023). "In breast cancer xenograft models with OGT deficiency, the tumor growth is reduced." (PMID 34899373, 2021). "OGT knockdown via sh-OGT reduces O-GlcNAcylation, activates endoplasmic reticulum stress, and triggers apoptosis in breast cancer cells, ultimately inhibiting tumor growth." (PMID 41280891, 2025). "Here, using a global proteomic analysis, we identified GATAD2B of the NuRD complex as a target of OGT and O-GlcNAc in breast cancer." (PMID 40136647, 2025). "Consistent with previous studies, overexpression of OGT significantly increased mammosphere formation in breast cancer cells compared to control." (PMID 40136647, 2025). "We for the first time showed that GATAD2B is critical for CSCs function in breast cancer and is regulated directly by OGT via O-GlcNAcylation." (PMID 40136647, 2025). "Collectively, we showed a novel regulatory mechanism of GATAD2B by OGT, which is pivotal for CSCs maintenance and function in breast cancer." (PMID 40136647, 2025). "In the same way, an increase in the percentage of radio-induced senescent breast cancer cells had also been observed upon the silencing of OGT." (PMID 39426963, 2024). "A previous study showed that an OGT inhibitor significantly inhibited breast cancer cell invasion and metastasis." (PMID 38213773, 2024). "In the context of breast cancer, research indicates that the expression levels of OGT are elevated in poorly differentiated tumors, and that the suppression of OGT activity can lead to a reduction in tumor growth." (PMID 39497715, 2024). "It has been shown that the proteome of MCF-7 breast cancer cells undergoes significant changes due to altered O-GlcNAcylation by siRNA-induced downregulation of OGT." (PMID 38473405, 2024). "The results of many studies suggest that increased expression of OGT and elevated O-GlcNAcylation are the common features of cancer, including breast cancer." (PMID 38473405, 2024).
breast carcinoma (continued). "Reginato’s team demonstrated that reducing OGT expression significantly decreases FoxM1 protein levels, inhibiting breast cancer cell growth and invasion." (PMID 39285476, 2024). "Depletion of KLF8 was able to abolish the effect of OGT overexpression in regulating mammosphere formation in TNBC cells, confirming the role of KLF8 downstream of OGT in breast cancer cells." (PMID 37152043, 2023). "KLF8 and OGT co-regulate each other to form a feed-forward loop to promote CSCs phenotype and mammosphere formation of breast cancer cells." (PMID 37152043, 2023). "Inhibitions of OGT and O-GlcNAc lead to reduced glycolysis and survival in breast cancer cells, suggesting a potential regulation of glycolysis by OGT and O-GlcNAc." (PMID 37838167, 2023). "In breast cancer and colorectal cancer, a key regulator of the cell cycle, cyclin D1, is directly modified by OGT." (PMID 37838167, 2023). "Immunoblot analysis of MDA-MB-231 cells overexpressing KLF8 showed both OGT and O-GlcNAc was elevated suggesting a potential feedback loop between KLF8 and OGT in breast cancer cells." (PMID 37152043, 2023). "Our previous study identified OGT and O-GlcNAc as a key driver of tumor initiation and stemness of breast cancer cells." (PMID 37152043, 2023). "The mTOR signaling pathway also provides a feedback mechanism to regulate OGT and O-GlcNAc levels in breast cancer cells." (PMID 37838167, 2023). "The transcription factor HIF-1α, which is stabilized under hypoxic conditions, is protected from degradation by OGT and O-GlcNAc in breast cancer cells even under normoxia." (PMID 37838167, 2023). "Elevated levels of OGT and O-GlcNAc in breast cancer led to an increase in cancer stem-like cell populations, as well as the tumor initiation capacity of breast cancer cells." (PMID 37838167, 2023). "Specifically, elevated OGT/O-GlcNAcylation is sufficient to drive CSCs properties of breast cancer cells, as well as lung and colon cancer cells." (PMID 37152043, 2023). "Knockdown of serine/arginine-rich protein-specific kinase 2 (SRPK2) resulted in an impairment of de novo lipogenesis similar to the phenotype observed in breast cancer cells with OGT depletion." (PMID 37838167, 2023). "O-GlcNAcylation, along with OGT are found to be highly elevated in a variety of cancers including breast cancer." (PMID 37152043, 2023). "Combined treatment of OGT inhibitor and Bortezomib efficiently induces apoptosis in breast cancer cells." (PMID 37838167, 2023). "Elevated mTOR activity in breast cancer cells enhances the expression of c-MYC to increase OGT level via upregulating HSP90A, which protects OGT from degradation by proteasome." (PMID 37838167, 2023). "In breast cancer, silencing OGT expression reduces mTOR expression and impairs cancer cell proliferation." (PMID 37838167, 2023). "Breast cancer cells depleted of OGT also showed a reduction in sterol regulatory element binding protein 1 (SREBP-1) expression." (PMID 37838167, 2023). "Abnormal expression of OGT has been showed to be related to the occurrence and development of several cancer types, including PC, breast cancer, colorectal cancer and other malignant tumors." (PMID 36439421, 2022). "In this study, we showed that mutation of MORC2 O-GlcNAcylation site (T556A) or pharmacological inhibition of OGT by OSMI-1 impairs MORC2-mediated breast cancer cell migration and invasion in vitro and lung colonization in a mouse xenograft mouse model." (PMID 34974534, 2022). "In breast cancer, reducing intracellular O-GlcNAcation by inhibiting OGT attenuates the expression of the transcription factor FoxM1, further resulting in the downregulation of downstream target genes and inhibiting tumorigenesis." (PMID 36275679, 2022). "Studies have confirmed that OGT is highly expressed in liver tumors, colon tumors, bladder cancer, and breast cancers." (PMID 36544170, 2022).
breast carcinoma (continued). "In this study, we uncovered several interesting findings concerning the functional and mechanistic role of OGT-mediated MORC2 O-GlcNAcylation in breast cancer progression." (PMID 34974534, 2022). "Various research groups have shown that OGT and O-GlcNAc levels increase during the progression of breast cancer which correlates with the histological grade of the tumor." (PMID 36439421, 2022). "Collectively, these results suggest that MORC2 O-GlcNAcylation is critical for breast cancer progression, which can be blocked by OGT inhibitor OSMI-1." (PMID 34974534, 2022). "Recently, tamoxifen-resistant breast cancer cell lines treated with OGT small molecule inhibitor OSMI-1 showed anti-tumor activity via epigenetic activation of the tumor-suppressor ERRFI1." (PMID 34771527, 2021). "OGT has been reported to promote EZH2 expression by stabilizing OGT in breast cancer cells while EZH2 has been indicated to facilitate CKD occurrence." (PMID 34462420, 2021). "Exemplary, in breast cancer cell lines, the O-GlcNAcylation and the regulating enzyme, O-GlcNAc transferase (OGT), are found to regulate the transcription factor HIF1α and thereby GLUT-1 expression." (PMID 34899373, 2021). "The efficiency of siRNA and pmOGT-HaloTag co-transfection on OGT and O-GlcNAcylation levels in the nuclear, mitochondrial, and cytoplasmic fractions of the three breast cancer cell lines was verified by Western blot." (PMID 34204801, 2021). "The results of many studies suggest that increased expression of OGT and hyper-O-GlcNAcylation are the universal features of cancers, including breast cancer." (PMID 34204801, 2021). "In vivo, OGT and O-GlcNAcylation levels are also increased in mouse mammary tumor induced by transgenic C-MYC." (PMID 35201498, 2021). "Overall, OSMI-1 represents an excellent tool compound to study OGT biology in vitro, and to discover possible strategies for anti-breast cancer therapy." (PMID 33046784, 2020). "OGT catalyzing O-GlcNAcylation of EZH2-S75 strengthens EZH2 stability, which means that OGT inhibitors (such as OSMI-1) are possible therapeutic targets for breast cancers." (PMID 33308321, 2020). "The degradation of endogenous OGT was found to be more susceptible to XIAP WT in HCT116 cells than in lung and breast cancer cells." (PMID 32994395, 2020). "Elevated OGT proteins, as well as O-GlcNAcylation level, are also found in both breast cancer cells and tumor tissues." (PMID 33194731, 2020). "Further research has revealed that O-GlcNAcylation of progesterone receptor (PR) by OGT transcriptionally activates its target genes, and PR-positive breast cancers express higher levels of OGT." (PMID 33194731, 2020). "Ac-5SGlcNAc treatment also blocks serum-stimulated cyclin D1 synthesis during the G0/G1 transition of breast cancer cells, suggesting that the role of OGT inhibitors in regulating the cell cycle further affects cell proliferation." (PMID 33194731, 2020). "For example, miRNA-24, miRNA-101, and miRNA-483, all of which decrease OGT transcription, have been shown to inhibit the invasive ability of breast cancer, CRC, and gastric cancer, respectively." (PMID 33194731, 2020). "In breast cancer cells, Nrf1 can be stabilized by OGT through O-GlcNAcylation at Ser448 and Ser451, a modification that suppresses the ubiquitin-proteasome mediated degradation of Nrf1." (PMID 33194731, 2020). "Professor Wong's team first provided convincing evidence on OGT-mediated EZH2 O-GlcNAcylation at S75 in breast cancer." (PMID 33308321, 2020). "In this study, we probed the importance of O-GlcNAc transferase (OGT) activity for the survival of tamoxifen-sensitive (TamS) and tamoxifen-resistant (TamR) breast cancer cells." (PMID 33046784, 2020). "Increased OGT expression and higher global O-GlcNAcylation levels suppress E-cadherin expression, thereby promoting breast cancer metastasis to the lungs." (PMID 33194731, 2020).